PCDHGA3 (protocadherin gamma subfamily A, 3)
Description:
Potential calcium-dependent cell-adhesion protein. May be involved in the establishment and maintenance of specific neuronal connections in the brain.
Synonyms: PCDH-gamma-A3
Tractability: Antibody: UniProt places it where antibodies can reach, with medium confidence; UniProt predicts a signal peptide or a membrane-spanning region; its Gene Ontology location is reachable by antibodies, with medium confidence. PROTAC: its protein half-life has been measured.
Gene: Protein-coding gene on chromosome 5 (141,343,829 to 141,512,975, forward strand). Ensembl gene ENSG00000254245.
Subcellular location: Cell membrane
Subcellular location (Human Protein Atlas): Plasma membrane; Vesicles; Cytosol; Nucleoplasm
Gene Ontology:
Molecular function: protein binding; cell adhesion molecule binding; calcium ion binding
Biological process: cell adhesion; homophilic cell-cell adhesion
Cellular component: plasma membrane; membrane
Genetic constraint (gnomAD): Loss-of-function variants: 40 observed, 61.46 expected, observed/expected ratio (o/e) 0.65, 90% interval 0.5 to 0.85. The upper end of that interval is the gene's LOEUF score, 0.85, which puts it in group 3 of 6, group 1 being the genes least tolerant of losing a copy. Missense variants: 1,223 observed, 1,252.3 expected, observed/expected ratio (o/e) 0.98, 90% interval 0.93 to 1.02. Synonymous variants: 530 observed, 545.84 expected, observed/expected ratio (o/e) 0.97, 90% interval 0.9 to 1.04.
Homologues: Orthologues: mouse Pcdhga3 (85% identical). Paralogues in human: PCDHGA2 (78% identical), PCDHGA4 (77% identical), PCDHGA6 (76% identical), PCDHGA8 (76% identical), PCDHGA1 (75% identical), PCDHGA10 (75% identical), PCDHGA7 (75% identical), PCDHGA5 (75% identical), PCDHGA12 (74% identical), PCDHGA11 (74% identical), PCDHGA9 (73% identical), PCDHGB2 (51% identical), and 49 more.
Diseases named in the same sentence as PCDHGA3 in open-access papers:
PCDHGA3 is named in the same sentence as 9 diseases in open-access papers, as found by Europe PMC text mining. Sharing a sentence is not in itself a finding about the gene and the disease. The quoted sentences say what the papers report.
ischemic cardiomyopathy (3 papers, 2016 to 2024). Ischemic cardiomyopathy is a cardiomyopathy in which a weakness in the muscle of the heart due to inadequate oxygen delivery to the myocardium with coronary artery disease being the most common cause. "In another gamma-protocadherin, PCDHGA3, the gene expression levels relate to ventricular dysfunction in patients with ischemic cardiomyopathy, indicating the role of this protein cluster for heart functionality." (PMID 37160609, 2023).
cancer (3 papers, 2019 to 2025). A tumor composed of atypical neoplastic, often pleomorphic cells that invade other tissues. "Using CAMDAC cancer-cell-specific methylomes as input for MethSig, we observed significant enrichment of hypermethylated candidate NSCLC cancer genes known to encode differentiation and developmental transcription factors, such as PCDHGA3 and EVX1, and in ZNF-154, which may affect plasticity." (PMID 40931149, 2025).
tumor (2 papers, 2009 to 2023). "These include PCDHGA3, hypermethylated in 24/27 tumours (89%), PCDHGB4 (23/25, 92%), PCDHGA2 (11/13, 85%) and PCDHB3 (21/33, 64%)." (PMID 19956686, 2009). "Analysis of PCDH methylation in microdissected perilobar nephrogenic rests, presumptive WT precursor lesions, revealed no PCDH hypermethylation but hypermethylation was evident at the PCDHGA3 and PCDHGB4 genes in a set of stromal-predominant tumours." (PMID 19956686, 2009). "IL1RL1, PCDHGA3, STMN2, and UGT2B11 showed no expression with tumor microenvironment components." (PMID 37985782, 2023).
PCDHGA3 also shares sentences with these, for which no sentence is quoted: brain tumors (1 paper); breast carcinoma (1); follicular lymphoma (1); septal defects (1); Sotos syndrome (1); Stroke (1).